EGFR (epidermal growth factor receptor)
Diseases named in the same sentence as EGFR in open-access papers (continued):
Sharing a sentence is not in itself a finding about the gene and the disease.
breast carcinoma (continued). "Previous studies showed that EFs are able to orientate the redistribution of EGFR on the surface of breast cancer cell membranes toward the anode and polarize the EGFR of mesenchymal stem cells and keratinocytes toward the cathode." (PMID 39852131, 2024). "Although the sample size is limited, these clinical sample results further corroborate our findings on STAT3-mediated SUSD2 upregulation in EGFR+ HER2+ breast cancer, underscoring the clinical significance of SUSD2 expression." (PMID 39791720, 2024). "A combination of oHSV and epidermal growth factor receptor (EGFR)-specific CAR-NK92 cells has shown increased tumor-killing efficacy against breast cancer and brain metastatic cells, leading to better survival outcomes." (PMID 39066359, 2024). "Previous studies have implied that the simultaneous expression of EGFR and HER2 is associated with breast cancer aggressiveness." (PMID 39791720, 2024). "By undergoing targeted retraining with specific cohorts, MuMo can swiftly adapt to different cancers such as breast cancer or to other clinically relevant immunohistochemical (IHC) markers like ER, PR, and EGFR." (PMID 39183247, 2024). "An EGFR mutation resulting in the loss of its extracellular domain in EGFR type III can cause constitutive activation and has been associated with lung, ovary, and breast cancers." (PMID 38601214, 2024). "Previously, we reported that gefitinib, a clinically relevant EGFR inhibitor, induces autophagy in various models of breast cancer in vitro." (PMID 39861690, 2024). "Eight biomarkers comprising ER, PR, HR, HER2, nm23-H1, CK5/6, EGFR, and Ki-67 were investigated for their effect on pCR outcome in Asian breast cancer patients treated with NAC TA." (PMID 38576013, 2024). "Its impact extends to gene regulation, including the inhibition of breast cancer development by targeting genes like the epidermal growth factor receptor (EGFR)." (PMID 38504785, 2024). "Breast cancer patients who have EGFR overexpression have larger tumors, poorer clinical outcomes, and poorer differentiation." (PMID 38808816, 2024). "The combination of breast cancer-targeting drugs with EGFR-TKIs holds promising potential in significantly enhancing drug efficacy, underscoring the importance of discovering a newer generation of EGFR-TKIs for breast cancer treatment." (PMID 38751788, 2024). "Another pre-clinical study showed EGFR to be highly expressed in basal-like TNBC, together with PYK2 and FAK, implicated in the progression and invasion of breast cancer." (PMID 38473804, 2024). "In breast cancer, high EGFR expression is found in TNBC subtype, however, analysis of the TCGA-BRCA cohort reveals that BMP8A expression is lower in TNBC compared to the other three subtypes." (PMID 39100096, 2024). "Although MCF7 cells express lower levels of EGFR compared to other breast cancer cell lines, EGFR signaling pathways still significantly affect MCF7 cell biology." (PMID 39194519, 2024). "have also indicated that IGFBP3 enhances the oncogenesis and development of breast cancer; mechanically, it can upregulate the EGFR phosphorylation and activate the p44/42 and p38 MAPK classical signaling pathways." (PMID 38463397, 2024). "YBX1 overexpression also induces constitutive activation of the epidermal growth factor receptor (EGFR), which contributes to the proliferation of breast cancer cells." (PMID 38255791, 2024). "EGFR is reported to be expressed in all molecular sub-types of breast cancer and over-expressed in triple-negative breast cancers." (PMID 39598379, 2024). "Elevated EGFR levels in gastric and breast cancers correlate with poor overall survival, advanced clinical stage, and resistance to therapy, emphasizing its prognostic relevance across various tumors." (PMID 39193333, 2024). "ORes inhibits breast cancer cell growth by inducing ferroptosis through suppression of the EGFR/PI3K/AKT/GPX4 signalling axis." (PMID 39881871, 2024).
breast carcinoma (continued). "Similar results were found in breast cancer; EGFR/STAT3 has been recognized as a critical signal axis for primaquine-mediated c-Myc down-regulation to induce apoptosis in breast cancer cells." (PMID 39338323, 2024). "Effect of designed‐synthesized small molecules as potential epidermal growth factor receptor inhibitors on proliferative potential of breast cancer and control cells." (PMID 38522013, 2024). "It was found that PA-MSHA inactivates EGFR signaling in bladder, pancreatic, and breast cancer cells and in vivo in tumor-bearing mice." (PMID 38339275, 2024). "In this study we demonstrate how factors secreted by brain endothelial cells (BEC) activate EGFR signalling via DOCK4 to promote an elongated phenotype in breast cancer cells, thereby facilitating their successful extravasation to the brain." (PMID 38762624, 2024). "In the present study, we determined that EGFR knockdown in breast cancer cells inhibited GPX4 expression." (PMID 39881871, 2024). "Molecular docking studies indicated strong inhibition of breast cancer proteins HER1 and HER2 (human epidermal growth factor receptors) by GST compounds." (PMID 39719988, 2024). "While this study demonstrated that ORes exerted anti-breast cancer activity by inducing ferroptosis through the inhibition of the EGFR/PI3K/AKT/GPX4 signalling axis, it is important to note some limitations." (PMID 39881871, 2024). "In terms of inhibition of angiogenesis, a study involving head, neck, and breast carcinomas found that EGCG at 30 μg/mL reduced VEGF production by interfering with epidermal growth factor receptor (EGFR)-related pathways." (PMID 39272454, 2024). "The results showed that, in breast cancer subtypes such as Her2, Luminal A, and Luminal B, the EGFR levels were only significantly expressed in stage 4." (PMID 39202273, 2024). "Our previous investigation on alkylaminophenols such as THTMP, THMPP, and HNPMI as effective inhibitors of EGFR has been reported against breast cancer, glioblastoma, and osteosarcoma, which motivated us to unravel its potential against CRC." (PMID 37183661, 2024). "The MDA-MB-231 cell line is a widely employed human breast cancer cell line known for its overexpression of EGFR, a protein pivotal in cell growth and proliferation." (PMID 39525484, 2024). "The preclinical pharmacodynamic studies demonstrated that lapatinib exhibited potent inhibition of HER2 and EGFR signaling, resulting in a significant reduction in tumor growth in breast cancer models." (PMID 38611728, 2024). "Although CAR-NK cells targeting CD44v6, HER2, TF, B7-H6, EGFR, and PD-L1 have made great progress in breast cancer, developing targets for CAR-NK cells in breast cancer has great research potential." (PMID 38680498, 2024). "Recently, we have reported that the survival rate of EGFR+ and HER2+ breast cancer patients is significantly lower than that of EGFR+ breast cancer patients." (PMID 39791720, 2024). "An in-silico study revealed its ability to combat breast cancer by inhibiting the HER2/EGFR/HIF-1α pathway through molecular docking." (PMID 38474594, 2024). "Induce cross-linking of T cells and EGFR-expressing breast cancer cells and elicit potent antitumor immunity." (PMID 39204374, 2024). "In this study, restoring of miR-770-5p regulated EGFR/HER2/IGF1R crosstalk signaling in HER2+ breast cancer cells." (PMID 39051060, 2024). "It is vital to identify the likely biological processes and cellular functions by which PTGS2/ESR2/EGFR/JUN/MMP2 genes’ signature exhibited their tumorigenic effect in breast cancer." (PMID 39707884, 2024).
breast carcinoma (continued). "The aim of this study was to evaluate the protein expression status of EGFR and VEGF-A, as well as their association with hormone receptor status and histopathological characteristics in the invasive type of female breast cancer among Ethiopians." (PMID 39405290, 2024). "Overall, EGFR, which was previously shown to be transcriptionally regulated by YB‐1 in breast cancer cells, showed an excellent fit in expression levels with YB‐1." (PMID 36550787, 2024). "The binase-EGFR protein complex was detected on the cell membrane of the triple-negative BT-20 breast cancer cell line overexpressing EGFR 1 min later of cell treatment with binase." (PMID 38374954, 2024). "Seventy-three downregulated and seven upregulated genes were identified, with EGFR and ANXA1 identified as the pivotal genes associated with breast cancer progression." (PMID 38794206, 2024). "Intravenous liposomal HCQ or free HCQ given intraperitoneally (IP) was assessed in combination with the autophagy-inducing EGFR inhibitor gefitinib in immunocompromised mice bearing established gefitinib-resistant JIMT-1 breast cancer xenografts." (PMID 39861690, 2024). "There is also growing evidence supporting afatinib’s utility in treating other EGFR and Her2-driven cancers, including breast cancer." (PMID 38892307, 2024). "It selectively engages with both HER2 and epidermal growth factor receptor (EGFR) tyrosine kinases, pivotal players in the unfolding narrative of breast cancer advancement." (PMID 38474678, 2024). "It has been previously reported that EGF is able to induce MIF expression in MCF10CAT breast cancer cells as well as in A431 cervical cancer cells through EGFR/MEK/ERK1/2 signaling pathway." (PMID 38145300, 2024). "This ADC restricted EGFR-expressing cancer cell growth in vitro and in xenografts while showing safe in vivo administration and low effects against EGFR-low breast cancer and immune cell models." (PMID 38772416, 2024). "EGF-induced lipid raft localization of the EGFR-ErbB2 heterodimer is crucial for Akt phosphorylation and breast cancer cell proliferation." (PMID 39329960, 2024). "While their study focuses on the EGFR pathway’s impact on immune cell dynamics, our research broadens the scope to identify inflammatory-driven molecular subtypes across breast cancer." (PMID 38728446, 2024). "In the presence of HB-EGF, a study in breast cancer cells showed that CD44v3 is required for activation of EGFR." (PMID 38761292, 2024). "Further research utilized quantum dots conjugated with an EGFR antibody for the in vivo imaging of metastasis in human breast cancer cells within mice." (PMID 38730959, 2024). "One of the characteristics that distinguishes TNBC from other breast cancer types is that most (approximately 50–80%) TNBC patients highly express epidermal growth factor receptor (EGFR)." (PMID 38604999, 2024). "Abnormal expression or activation of EGFR and its downstream pathways is common in various cancers, such as gastric cancer, colorectal cancer, and breast cancer." (PMID 39606630, 2024). "Overexpression of YBX1 in breast cancer induces EGFR expression and vice versa, in which the pivotal role of S102 is proved in YBX1 binding EGFR promoter capability." (PMID 38255791, 2024). "Encouragingly, our findings demonstrate a significant association between the drug response to gefitinib and erlotinib and a gained active SCRE ("Pair_92_SCRE61’, a super-enhancer cataloged in Reference) in EGFR specific to basal breast cancer." (PMID 38213995, 2024). "The iRGD and GE11 exosomes showed preferential accumulation in αv integrin-positive and EGFR-overexpressing breast cancer cells." (PMID 38172932, 2024). "Among HER2-enriched breast cancer population, the close interplay between EGFR and HER2 receptors also contributes to poor prognosis, as patients with co-expression of these proteins often exhibit therapy resistance." (PMID 39768978, 2024).
breast carcinoma (continued). "EGFR is often overexpressed in breast cancer and particularly triple-negative breast cancer (TNBC), which currently lacks molecular targets." (PMID 38474312, 2024). "In breast cancer, recent findings also indicate that the loss of PTPN12 phosphatase function activates several oncogenic RTKs such as MET, PDGFRb, HER2, and EGFR, positioning PTPN12 as a master regulator of protein tyrosine kinases." (PMID 38612874, 2024). "IHC staining revealed elevated SUSD2 protein levels in tissues from a patient (Case 1) with EGFR+ HER2+ breast cancer compared to tissues from a patient (Case 2) with EGFR+ breast cancer." (PMID 39791720, 2024). "GW633459A is a lapatinib analog synthesized during the development of a EGFR/HER2 dual inhibitor to treat breast cancer." (PMID 38590439, 2024). "Tandyukisin has demonstrated the ability to inhibit cancer cell growth in the micromolar range, selectively target EGFR-amplified breast cancer cell proliferation, and induce apoptosis through Caspase-3 activation." (PMID 38751788, 2024). "In a human breast cancer cell model, one recent study found that there was a positive correlation between the expression of TGF-β and EGFR, an important growth factor known to be overexpressed in breast cancer." (PMID 38926762, 2024). "To further investigate the role of EGFR in the response of breast cancer cells to BEC-secreted factors, we treated the cells with Afatinib, an inhibitor of the ErbB family kinases, including EGFR32." (PMID 38762624, 2024). "Third, the current study observed the association between EGFR amplification, CCL2 upregulation and accumulation of TAM subtypes, which is supported by studies in GBM and breast cancer." (PMID 38515213, 2024). "In this study, we uncovered that ORes induces ferroptosis in breast cancer cells through the inhibition of the EGFR/PI3K/AKT/GPX4 signalling axis." (PMID 39881871, 2024). "GEPIA2 database analysis revealed significant downregulation of PIK3R1, AKR1C3, and EGFR mRNAs in breast cancer tissue, with ESR1 upregulation, pointing to a complex interplay in tumorigenesis and treatment response." (PMID 39204124, 2024). "This stimulation is accompanied by EGFR activation necessary for brain metastatic breast cancer cell elongation which can be reversed by the EGFR inhibitor Afatinib." (PMID 38762624, 2024). "Quantum dot-based quantitative immunofluorescence was employed to detect and analyze the expression of the epidermal growth factor receptor (EGFR) in breast cancer tissue arrays." (PMID 38730959, 2024). "Collectively, these findings suggest that ORes induces ferroptosis in breast cancer cells by inhibiting the EGFR/PI3K/AKT/GPX4 signalling axis." (PMID 39881871, 2024). "While the role of HER4 in breast cancer is controversial, EGFR, HER2, and HER3 are strongly implicated in breast cancer." (PMID 39273024, 2024). "Some biomarkers, which have been mentioned here, and researched for their clinical utility in locating and characterizing breast cancer include EGFR, HER2, ER, CD24, CD44, and CD47." (PMID 40051976, 2024). "Tspan8 upregulation promotes breast cancer stemness and drug resistance.Tspan24 binds to integrin α6 and EGFR." (PMID 38649381, 2024). "The methylation status of the HIF binding region within the hypoxia response element correlates with increased expression of epidermal growth factor receptor (EGFR) under hypoxic conditions in breast cancer." (PMID 38279330, 2024). "One study reported that the overexpression of SSTR2 induces apoptosis in breast cancer cells, decreases epidermal growth factor receptor expression, and exhibits antiproliferative effects." (PMID 39238765, 2024). "This method helped identify the significance of EGFR expression in specific subgroups of the patients with breast cancer, enhancing the understanding of its role in cancer prognosis." (PMID 38730959, 2024).
breast carcinoma (continued). "HBEGF, a ligand for EGFR, has been specifically identified in brain metastasis and demonstrated to enhance invasion in breast cancer cells." (PMID 38714954, 2024). "Since our previous results demonstrated the upregulation of SUSD2 in EGFR+ HER2+ breast cancer cells, we aimed to further explore this association in clinical samples." (PMID 39791720, 2024). "Overall, our findings demonstrate that ORes is a novel ferroptosis inducer that exerts anti-breast cancer effects by inhibiting the activation of the EGFR/PI3K/AKT signaling pathway." (PMID 39881871, 2024). "EGFR overexpression in breast cancer, especially triple-negative breast cancer (TNBC), is associated with large tumor size, poor differentiation, and poor clinical prognosis." (PMID 38706904, 2024). "BEC-conditioned media promote EGFR activation, breast cancer cell elongated morphology and filopodial protrusions; and knockdown of either DOCK4 or RAC1 reverses cancer cell elongation without affecting filopodia." (PMID 38762624, 2024). "Although clinical trials using gefitinib as a monotherapy for breast cancer have exhibited unsatisfactory results, immunohistochemical analysis of post-treatment breast tumors has revealed complete inhibition of EGFR phosphorylation." (PMID 38476263, 2024). "Promotion of invasion and migration of breast cancer cells by TAMs to distant sites by secreting EGF which binds to EGFR on breast cancer cells has been observed." (PMID 38703051, 2024). "This discovery suggests a novel therapeutic approach, whereby the interaction between EGFR and copper can be explored further in breast cancer treatment." (PMID 39702350, 2024). "Capivasertib (TruqapTM) is used in combination with fulvestrant (FaslodexTM) for the treatment of patients with hormone-receptor-positive, human-epidermal-growth-factor-receptor-2-negative breast cancer with metastatic disease." (PMID 38338330, 2024). "Other targets showing promise in preclinical breast cancer models include epidermal growth factor inhibitor (EGFR) and vascular endothelial growth factor (VEGF)." (PMID 38611020, 2024). "In E-cadherin-positive MDA-MB-231 human breast carcinoma cells, E-cadherin also forms a complex with EGFR." (PMID 39594667, 2024). "In order to determine the mechanism of TRPV3 mediated migration, proliferation and apoptosis of breast cancer cells, we identified EGFR as a key mediator." (PMID 38706904, 2024). "In breast cancer cell lines, hypoxia can modulate EGFR expression and downstream signalling in a DNA methylation‐specific and HIF‐dependent manner, altering the response to anti‐EGFR therapy." (PMID 38013642, 2024). "Tanshinlactone selectively inhibits the growth of ER+ and HER2+/EGFR + breast cancer cells while showing limited cytotoxicity against other cancer types and normal cells." (PMID 39906392, 2024). "Currently, tyrosine kinase inhibitors (TKIs) are the primary targeted therapy for patients with HER2/EGFR-positive breast cancers." (PMID 39906392, 2024). "Beyond EGFR’s classical role in promoting glioma cell proliferation and survival through the activation of oncogenic PI3K, AKT and RAS/MAPK pathways, EGFR overexpression has been linked with macrophages recruitment in GBM and breast cancer." (PMID 38515213, 2024). "This specificity is particularly significant in breast cancer cells with high EGFR expression levels." (PMID 38543204, 2024). "A small molecule compound S62, which inhibits the PELI1/EGFR interaction has depicted an effective strategy for inhibiting breast cancer metastasis." (PMID 38522013, 2024). "CAR-NK cells targeting CD44v6, HER2, TF, B7-H6, EGFR, and PD-L1 have been successfully used for treating different types of breast cancer." (PMID 38680498, 2024). "In summary, a novel CS-based nano-complex modified with carboxyl and functionalized with DNA-Apt (as targeting and therapeutic agent) was designed and synthesized for the effective delivery of NO into EGFR-positive breast cancer cells." (PMID 39435057, 2024).